IDH1 (isocitrate dehydrogenase (NADP(+)) 1)
Diseases named in the same sentence as IDH1 in open-access papers (continued):
Sharing a sentence is not in itself a finding about the gene and the disease.
glioma (continued). "When wildtype Idh1 was expressed instead of mutant Idh1 in the same background, only 20% of the injected mice developed glioma." (PMID 36765553, 2023). "Because of its prognostic significance, IDH1 has emerged as a therapeutic target and IDH1 inhibitors are being studied in solid tumors including gliomas (NCT 02073994, NCT 02381886)." (PMID 37621817, 2023). "Glioma samples tested by the brain subpanel had BRAF variants at 8% and IDH1/IDH2 variants at 12.5%." (PMID 37483495, 2023). "Mutant IDH1 and O6-methylguanine DNA methyltransferase (MGMT) promoter methylation associate with well prognostic outcomes of glioma patients." (PMID 38027011, 2023). "First, knockdown of DNMT1 dramatically inhibited the replication of VSVΔ51 in glioma cells expressing IDH1(R132H)." (PMID 37880243, 2023). "Increasing evidence has revealed the feasibility of using MRI to predict the type of glioma and molecular biomarkers, such as IDH1, Ki67, and H3-K27M, via machine learning or deep learning method." (PMID 37248527, 2023). "Two other peptide vaccines against mIDH1 are being studied: PEPIDH1M in patients with recurrent grade 2 gliomas (RESIST trial NCT02193347) and IDH1 R132H dendritic cell vaccine in patients with IDH mutant gliomas (NCT02771301)." (PMID 37060388, 2023). "The BBB-penetrant IDH1 inhibitor DS-1001b was evaluated in a phase I clinical trial in adult patients with IDH1-mutant recurrent/progressive glioma with promising results." (PMID 37781183, 2023). "It has three isoenzymes encoded by five genes, with IDH-1 and IDH-2 involved in developing human Gliomas." (PMID 37193447, 2023). "Previous studies have used 1p/19q chromosomal codeletion, mutations of IDH1/2, and MGMT promoter methylation as three molecular biomarkers to guide the classification and treatment decisions of glioma." (PMID 37837543, 2023). "Here, the authors show that D2HG produced by mutant IDH1 inhibits IFN antiviral responses in glioma cells, which confers sensitivity to oncolytic virotherapy." (PMID 37880243, 2023). "IDH1 and IDH2 mutations are commonly found in low-grade glioma (70% of WHO grade 2 and 3 astrocytomas and oligodendrogliomas) and secondary GBM (which is developed from lower-grade gliomas)." (PMID 37182181, 2023). "In this study, the authors genetically dissect patient-derived IDH1 mutant cultures to determine which HDAC enzymes drive growth in IDH1 mutant gliomas." (PMID 37528157, 2023). "Mutations including IDH1, PDGFRA, ATRX, etc. have been identified to be associated with glioma tumorigenesis, tumor development and patients’ prognosis." (PMID 36720864, 2023). "Eleven patients with suspected lower-grade glioma (ten IDH1; one IDHwt) were prospectively included." (PMID 37685329, 2023). "In 104 glioma samples, we preliminarily finished the rapid detection of IDH1-R132H in 60 min using Crispr-Cas12a." (PMID 37029174, 2023). "As observed in clinical data of IDH1-mut AML patients, IDH1-mut glioma patients with high PDGFRA expression also showed significantly worse survival rates, supporting a strong clinical relevance of this mechanism." (PMID 36411356, 2023). "It should be noted that these studies used mixed populations of IDH1 wildtype and IDH1 mutant gliomas with IDH1 wildtype likely being the majority." (PMID 37528157, 2023). "IDH1 and IDH2 mutations have long been established in the molecular pathology of gliomas, and now form a core aspect of their diagnostic classification." (PMID 37444417, 2023). "Orthotropic grafts with the combination of IDH1 mutated and silenced GDH1,-2 glioma cells demonstrated a significant reduction in the tumor volume compared with grafts of control cells." (PMID 38139462, 2023). "IDH1 wildtype glioma demonstrated significantly more expression of all proteins: GAP-43 (p = 0.009), Cx43 (p = 0.003) and actin (p < 0.001)." (PMID 36739296, 2023). "The discovery of mutations in the IDH1 and IDH2 genes in gliomas has significantly impacted the classification and treatment of these tumors." (PMID 37212938, 2023).
glioma (continued). "In the case of glioma, it appears that additional therapies are needed to reverse the epigenetic dysregulation induced by the IDH1 mutant enzyme." (PMID 37528157, 2023). "Overall, our study reveals a hitherto unrecognized link between IDH1 mutation and IRF3/7 in antiviral immunity and provides a theoretical basis for clinical treatment of IDH1mut gliomas by oncolytic viruses." (PMID 37880243, 2023). "(Fig. 3B1) Our analysis also shows that the C1 subtype and the C2 subtype were significantly different in IDH1 mutations (Fig. 3B2), this accounts for the uneven distribution of MAPK subtypes within different glioma subtypes." (PMID 37925483, 2023). "TF expression enhances migration, adhesion, and proliferation in both IDH1 mutant and wild-type gliomas." (PMID 37280670, 2023). "A clinical trial has shown that a vaccine targeting the IDH1 mutant in patients with grade III or grade IV glioma elicited immune responses in both T and B cells." (PMID 37274252, 2023). "To explore more possible biomarkers for glioma, we performed a search of the literature and found the IDH1 G105G SNP." (PMID 36980973, 2023). "Mutant IDH has been found to reduce the infiltration of TAMs in both IDH1 mutant mouse models and human glioma tissues." (PMID 37296846, 2023). "The time interval between primary and reoperation was shorter for primary high-grade glioma and/or IDH1 wild-type tumor patients than for low-grade glioma and/or IDH1 mutant tumor patients (P < 0.001)." (PMID 36597096, 2023). "In this study, we reveal that polypeptide N-acetylgalactosaminyltransferase 5 (GALNT2) expression level was elevated in GBM, IDH1 wildtype glioma, and GBM stem cells (GSCs)." (PMID 37000153, 2023). "For example, mutations in the genes encoding isocitrate dehydrogenase (IDH) 1 and 2 (IDH1 and IDH2) account for approximately 80% of grade-2 gliomas and represent one of the fundamental and earliest molecular events in the genesis of these tumors." (PMID 37372381, 2023). "Taken collectively, these recent advances in producing genetically faithful GEMMs of IDH1 mutant glioma open new avenues to explore how this oncogene promotes gliomagenesis and creates therapeutic opportunities." (PMID 37051530, 2023). "Montanide ISA-51 was also used as adjunctive immunotherapy in an early-phase trial (NOA16; n = 32; NCT02454634) assessing the safety of an IDH1(R132H)-specific peptide vaccine in patients with another primary central nervous system tumor (IDH1 mutant glioma)." (PMID 37111620, 2023). "In gliomas, IDH mutations are found primarily in IDH1 (incidence > 70%), with R132H representing > 90% of all mutations identified." (PMID 37372972, 2023). "Other studies have identified transcriptional repressor activity with histone deacetylases, however this study found that in an IDH1 mutant glioma model (HK252), the HDAC genes activate a set of chromosome organization and DNA replication gene modules." (PMID 37528157, 2023). "IDH1 inhibitor ivosidenib delayed the progression of cancer cachexia in murine GL261 glioma model and CT26 colorectal carcinoma models." (PMID 37741882, 2023). "We find that IDH1 R132H point mutations also disrupt PML-NBs, suggesting that defective PML-NBs are a common oncogenic driver in gliomas and myeloid leukemias." (PMID 38066546, 2023). "The drug screen identified histone deacetylase inhibitors (HDACi) and panobinostat (LBH) more specifically as the most selective compounds to inhibit growth in IDH1 mutant glioma lines." (PMID 37528157, 2023). "Accordingly, inhibition of IDH1 by shRNA in glioma-initiating cells leads to increased histone trimethylation on H3K4, H3K9, H3K27, enhanced susceptibility to differentiation stimuli, and reduces stem cell frequency." (PMID 36768660, 2023). "For example – the adult glioma subtype of oligodendroglioma can be confirmed by presence of co-deletion of chr1p/19q and somatic alteration in IDH1." (PMID 36711972, 2023).
glioma (continued). "The IDH1 mutation rate was higher in NI subgroup II (82%) than NI subgroup I (36%), IDH1 mutation dramatically indicated the outcome of glioma patients, so the distinction in IDH1 mutation between two cluster subgroups may contribute to the prognosis of glioma." (PMID 37351504, 2023). "A lower ALPS index was also observed in patients with wild-type IDH1 gliomas (compared to the IDH1 mutant) and gliomas with greater peritumoral edema." (PMID 37767530, 2023). "In this work, we first used the early-passage glioma cell cultures to compare hardness of IDH1 R132H mutant and IDH1 wild-type cells." (PMID 36835465, 2023). "Our finding of upregulated PDGFRA expression in connection with altered DNA looping in IDH1-mut AML now extends this mechanism of action beyond the context of glioma." (PMID 36411356, 2023). "Extracellular IDH1 directly enhanced T cell responses to multiple tumor antigens, and prolonged experimental glioma cell lysis." (PMID 37161052, 2023). "IDH1-dependent PARPi sensitivity has been shown in culture in patient-derived glioma cells as well as genetically matched tumor xenografts in vivo." (PMID 36968138, 2023). "In more detail, the binding of FOXO1 but not FOXO3a, FOXO4, or FOXO6 to cyclin F promoter subsequently represses the expression of IDH1 as a crucial proto-oncogene in glioma." (PMID 37821870, 2023). "The heterozygous IDH mutation, most commonly at an arginine (R) residue (i.e., IDH1(R132) or IHD2(R172)), results in the conversion of α‐ketoglutarate to 2‐hydroxyglutarate (2‐HG), a biomarker for IDH‐mutant gliomas." (PMID 36916606, 2023). "In recent years, isocitrate dehydrogenase 1 (IDH-1) has garnered interest for treating glioma patients." (PMID 37046685, 2023). "In a phase I trial, 30 patients with recurrent or progressive IDH1/2mt enhancing glioma received vorasidenib, an oral, brain-penetrant inhibitor of IDH1/2mt." (PMID 36968138, 2023). "Mutations in isocitrate dehydrogenase 1 (IDH1) gene – a crucial enzyme of TCA cycle, are associated with better prognosis in gliomas." (PMID 37476290, 2023). "Here, using the DSP platform, we have systematically evaluated data from a set of paired isocitrate dehydrogenase-1 (IDH1) R132H mutant glioma samples." (PMID 36590163, 2023). "Although numerous somatic mutations have been identified in IDH1/2 in tumors, there appears to be a predilection for specific binding site “hotspot” mutations (Arg 132 for IDH1, Arg 172 for IDH2) in certain diseases such as leukemia and glioma." (PMID 37371524, 2023). "Primary WHO low grade or IDH1 mutant gliomas appeared survival benefit mainly on later recurrence, but was not a prognostic predictor following recurrence." (PMID 36597096, 2023). "In WHO grade 3 glioma, IDH1/2-mutated gliomas have a median survival of ~ 3.5 years, whereas IDH1/2 wild-type gliomas have a median overall survival of 1.5 years." (PMID 36959545, 2023). "We found that FTL expression was significantly higher in IDH1/2 wildtype gliomas and 1p/19q non co-deletion." (PMID 37441589, 2023). "Most IDH1 DNA sequence alterations in gliomas occur as a single amino acid substitution with the hot spot at the arginine at codon 132 — R132H and cDNA coordinates—c.395G>A." (PMID 37908227, 2023). "We also established an orthotopic tumor model of in vivo bearing GL261 glioma cells with IDH1-mut in vivo." (PMID 37741882, 2023). "IDH1 decreases the cellular buffering ability against radiation-induced oxidative stress, thus enhancing the radiation sensitivity of gliomas." (PMID 37176148, 2023).
glioma (continued). "The mutations of IDH1/2 and TERT promoter were analyzed, and risk factors affecting survival of the patients with glioma were assessed." (PMID 37250582, 2023). "The authors highlighted how most patients who had a decrease in seizure activity had IDH1 mutant gliomas." (PMID 36831869, 2023). "Frequent mutations of IDH1 and IDH2 have been found in various tumors, such as acute myeloid leukemia (AML), glioma, and chondrosarcoma." (PMID 37563735, 2023). "Previous studies showed that intratumorally, 2-HG levels correlate with the cellular density of mutant IDH1 glioma tumours in which low tumour cellularity will lead to limited 2HG-MRS sensitivity for the detection of low 2-HG levels." (PMID 37238288, 2023). "Genomic analyses have revealed IDH1 or IDH2 mutations in samples from most patients with glioblastoma multiforme and grade II-III gliomas." (PMID 36959802, 2023). "As expected, VSVΔ51 infection activated IFN antiviral responses in glioma cells, while doxycycline-induced IDH1(R132H) appeared to inhibit VSVΔ51-induced activation of IFN signaling pathways." (PMID 37880243, 2023). "This study identifies HDAC1 and HDAC6 as important and drug-targetable enzymes that are necessary for growth and invasiveness in IDH1 mutant gliomas." (PMID 37528157, 2023). "Although there was no significant change in muscle weight was found, the expression of E3 ligases Trim63 and Fbxo32 was increased in the muscle of mice bearing IDH1 mutant glioma tumors, whereas it was attenuated after ivosidenib treatment." (PMID 37741882, 2023). "The IDH1- mutated glioma had significantly increased SLC7a11 expression following CMD, while the IDH1-wild-type glioma trended towards an increase of SLC7a11 (p = 0.08) (d ii.)." (PMID 36864031, 2023). "IDH1 and IDH2 mutations are found to be mutually exclusive in gliomas, and the presence of mutations in IDH1/IDH2 is associated with a favorable prognosis." (PMID 37371331, 2023). "After excluding IDH1 R132H mutant gliomas from the analysis, the specificity increased to 41.5% for EGFR, 53.2% for MEOX2, 50.7% for SOX11 and 57.3% for INSM1." (PMID 37568909, 2023). "It was found that the import of mutant IDH1 into the GL261 glioma tumor resulted in a significant improvement in survival." (PMID 37741882, 2023). "We found that TMEM158 mRNA expression increased with tumor grade, and its expression in IDH1-wild-type (IDH1-WT) gliomas of each grade was higher than that in IDH1-mutant (IDH1-Mut) gliomas." (PMID 34992215, 2022). "Although phase I clinical trials demonstrated a promising antitumor activity, further evidence indicated the limitations of IDH1-mutant inhibitors against glioma growth." (PMID 35436915, 2022). "Currently, the standard of care in the treatment of IDH1/2 mutant gliomas is maximal, safe surgical resection, with adjuvant radiotherapy and specific chemotherapy dependent on molecular subtype and grade." (PMID 35448183, 2022). "On the other hand, IDH1 wild-type glioma is the most aggressive form of glioma, and IDHwt patients only have a short survival time (6–12-months)." (PMID 35216362, 2022). "Our investigation indicated that TMEM158 expression was positively related to WHO glioma grade and was more highly expressed in IDH1-WT gliomas than in IDH1-Mut gliomas for each WHO classification grade." (PMID 34992215, 2022). "LGG, a diffuse low- and intermediate-grade glioma (WHO grades II and III), is a rare glioma that can be divided into different subtypes based on IDH1/2 mutation status and the presence of 1p19q co-deletion." (PMID 36338998, 2022). "The values of maximum TBF in high-grade IDH1-wildtype gliomas (n = 42) were 178.27 ± 104.99 mL/100 g/min, normalized values were 10.06 ± 5.91." (PMID 35741254, 2022).
glioma (continued). "Phase II study of IDH1 Inhibitor AG-120 in combination with nivolumab is being investigated in patients with IDH1 mutant gliomas." (PMID 35216362, 2022). "Both IDH1 (isocitrate dehydrogenase 1) and IDH2 (isocitrate dehydrogenase 2) mutations play a vital role in the development of gliomas through disruption of normal cellular metabolic processes." (PMID 36286062, 2022). "There is a phase II clinical trial that is specifically designed to look at the effectiveness of nivolumab in patients with IDH1 or IDH2 hypermutated gliomas (hypermutator phenotype) currently recruiting (NCT03718767)." (PMID 35203636, 2022). "Elevated HAUS1 expression (red and green) in the IDH1 mutation group indicated a dismal survival outcome, implying that HAUS1 was a significant prognostic factor for patients with glioma with the corresponding IDH1 genotypes (P < 0.001)." (PMID 35865089, 2022). "Twenty-two patients who underwent LITT for IDH1/2 mutant grade 2/3 glioma at a mean age of 46.6 years were included in this study." (PMID 35448183, 2022). "Since previous studies have shown that IDH mutations are closely related to the prognosis of glioma, we next analysed the role of IDH1 and IDH2 mutations in glioma by using the GSCA database." (PMID 35982398, 2022). "We also confirmed known associations between age and mutations in tumour suppressors IDH1- and ATRX- in both high grade glioblastoma and lower grade gliomas, IHD1- and ATRX- were more frequent in tumours derived of younger individuals." (PMID 35017538, 2022). "The presumed mechanism of the IDH1 mutation is to methylate cytosine nucleotides in DNA and induce a more closed inaccessible DNA chromatin with subsequent gene down-regulation however atac-seq data on IDH1 mutant glioma samples is limited." (PMID 35581287, 2022). "We identified six publications, with one conference abstract in addition; four publications reported co-occurring IDH1/2 mutations in acute myeloid leukaemia (AML), 1 in chondrosarcoma and 1 in glioma." (PMID 36286062, 2022). "Some studies have reported that IDH inhibitors inhibit the proliferation of IDH1 mutant glioma cells while other studies find it ineffective." (PMID 35806478, 2022). "Our study revealed significant difference in blood flow measured by the PCASL method in groups of gliomas with different IDH1 statuses." (PMID 35741254, 2022). "In the HGG subgroup, maximum TBF and normalized blood flow values were significantly higher in wildtype gliomas compared with IDH1-mutant ones (p < 0.001)." (PMID 35741254, 2022). "The heatmap showed that Nature-killer cell gene expression was correlated with WHO grade, IDH1 mutation, MGMT promoter methylation, 1p19q co-deletion, tumor subtype in glioma patients in CGGA and TCGA datasets." (PMID 35236310, 2022). "Increased radiosensitization of IDH1 mutant glioma cells was found in in vitro models through increasing apoptosis and upregulating ROS generation." (PMID 35216362, 2022). "A comparison of the expression level of HPGDS with the mutation status of IDH1 showed that HPGDS was more highly expressed in IDH1 wild-type gliomas, especially grade 2 and 4 gliomas." (PMID 36291099, 2022). "Specifically, 54.2% of female patients in low—expression miR-4297 group had IDH 1/2 mutation, whereas only 20.8% of subjects in high - expression miR-4297 group were IDH1/2-mutant gliomas." (PMID 35968285, 2022). "The most common non-FGFR1 alterations were IDH1/2 mutations (234 cases), KIAA1549-BRAF fusion (73 cases), 24 TERT C228/C250-mutated gliomas and 35 cases with NF1." (PMID 35018490, 2022).